MMP9 (matrix metallopeptidase 9)
Diseases named in the same sentence as MMP9 in open-access papers (continued):
Sharing a sentence is not in itself a finding about the gene and the disease.
glomerulosclerosis (7 papers, 2012 to 2024). A hardening of the kidney glomerulus caused by scarring of the blood vessels. "Moreover, as oestradiol modulates MMP (e.g., MMP-9, MMP-2) activity, as assessed in the development of glomerulosclerosis-associated renal injury, the effect of MMP-9 could be sex-specific." (PMID 34526107, 2021). "This indicated that the process of glomerulosclerosis involved intracellular degradation of cytosolic MMP-9." (PMID 23110201, 2012). "Previous studies of a rat model of tubulointerstitial fibrosis and glomerulosclerosis indicated reduced expression of MMP-9." (PMID 23110201, 2012). "With regard to the protective role of MMP-9 in CRF explored in the present study, investigating methods to increase MMP-9 levels is likely to be beneficial in the search for efficient therapies for tubulointerstitial fibrosis and glomerulosclerosis in CRF." (PMID 24396399, 2014). "The expression of TIMP-1 was downregulated, while the mRNA and protein expression and activities of MMP-2 and MMP-9 were enhanced after treatment with benazapril and all-trans retinoic acid (ATRA) in Wistar rat model of glomerular sclerosis compared to normal group." (PMID 23057632, 2012).
Hepatic steatosis (7 papers, 2014 to 2026). Steatosis is a term used to denote lipid accumulation within hepatocytes. "In this study, KMUP-1 increased IL-10 and decreased MMP-9 significantly, little affected TNFα, indicating its anti-inflammatory properties in hepatic steatosis." (PMID 27548140, 2016). "Interestingly, MMP9 expression in the liver of patients correlated positively (r=0.63, p=0.005) with ATI measurements, performed to evaluate liver steatosis." (PMID 40257301, 2025).
left ventricular hypertrophy (7 papers, 2015 to 2024). Enlargement of the LEFT VENTRICLE of the heart. "By the end of follow-up (March 2017), three patients had left ventricular hypertrophy, and all of them belong to the high MMP-9 group." (PMID 29693002, 2018). "Ang II treatment in the WT mice led to left ventricular hypertrophy, which was prevented in the MMP-9−/− mice." (PMID 27966586, 2016).
lupus nephritis (7 papers, 2012 to 2025). Glomerulonephritis in the context of systemic lupus erythematosus. "Additionally, glomerular MMP-9 staining were increased in the mesangial region and its levels correlated the glomerular cell proliferation in human lupus nephritis." (PMID 32655553, 2020). "The MMP2 and MMP9 mRNA levels were significantly up-regulated in class IV lupus nephritis." (PMID 22479529, 2012). "In sum, the vector that point at chromatin-IgG deposits in GBM are clustered with vectors pointing at TLR7–9, Clec4e, MMP2 and MMP9, indicating an interdependency between them, while the DNaseI vector points the opposite direction due to its negative correlation with advanced lupus nephritis." (PMID 22479529, 2012).
malignant mesothelioma (7 papers, 2003 to 2023). A malignant neoplasm of the pleura or peritoneum, arising from mesothelial cells. "Significantly, Nasu and colleagues demonstrated that ONC is a potent inhibitor of NF-κB activity in malignant mesothelioma, suggesting that the ONC blockage of NF-κB activation leads to the inhibition of MMP9 secretion and of its consequent invasiveness." (PMID 31783660, 2019). "In malignant mesothelioma, ONC inhibits Tumor Necrosis Factor-alpha (TNFα)-elicited NF-κB nuclear translocation and reduces MMP9 activity, as well as cell invasiveness." (PMID 31783660, 2019). "MM=malignant mesothelioma; UP=uninflammed pleura; IP=inflammed pleura; MMP-9=gelatinase B; MMP-2=gelatinase A." (PMID 12771921, 2003). "Malignant mesothelioma MSTO-211H cells did not secrete u-PA; however, MMP-9 secretion by MSTO-211H was inhibited by NM and secretion of TIMP-2 was enhanced by NM." (PMID 23563849, 2013). "For malignant mesothelioma MSTO-211H cells, a significant negative correlation (r=−0.955 was found between inhibition of NM modulation of Matrigel invasion and MMP-9 secretion." (PMID 23563849, 2013).
mastitis (7 papers, 2019 to 2025). Inflammation of breast tissue during lactation or postpartum due to an obstructed duct or infection. "The elevation of MMP-9 in endotoxin-induced mastitis milk was also confirmed in naturally occurring diseases." (PMID 37577188, 2023). "This study aimed to investigate the protein component and the activity of matrix metalloproteinase-2 (MMP-2) and -9 (MMP-9) in raw milk samples with different testing scores determined using the California mastitis test (CMT)." (PMID 37577188, 2023). "Among these, seven genes (CXCR1, HCK, IL1RN, MMP9, S100A9, GRO1, and SOCS3) were identified as the hub genes and these can be explored as potential candidate genes for mastitis susceptibility and resistance." (PMID 35723402, 2022). "Considering the specificity of biomarkers for rapid detection, IL8RB, CXCL6, and MMP9 were identified as the most potential biomarker for E. coli mastitis." (PMID 31921295, 2019). "Luteolin inhibited the expression of TNF-α, IL-1β, and IL-6; suppressed IκBα and NF-κB p65 phosphorylation levels; and downregulated the expression of MMP-2 and MMP-9 in S. aureus-induced mastitis, showing its potential in reducing tissue damage and inflammation caused by S. aureus-induced mastitis." (PMID 36111166, 2022). "Among these, seven genes—CXCR1, HCK, IL1RN, MMP9, S100A9, GRO1, and SOCS3—were identified as the hub genes (highly connected genes) for mastitis susceptibility and resistance, and were subjected to protein-protein interaction (PPI) network and gene regulatory network construction." (PMID 35723402, 2022). "Thus, it has been shown that certain enzymes, such as gelatinases (especially matrix metalloproteinases, MMP-2 and MMP-9) that degrade the basal membrane and interstitial proteins, have 300 times higher values in cow’s milk with colibacillary mastitis compared to milk from healthy animals." (PMID 33114454, 2020). "The most important overexpressed genes in cows with mastitis were GRO1, CXCR1, SOCS3, S100A9, MMP9, HCK, and IL1RN, which were hub genes (highly connected genes) involved in mastitis in this study." (PMID 35723402, 2022).
mesothelioma (7 papers, 2013 to 2022). A usually malignant and aggressive neoplasm of the mesothelium which is often associated with exposure to asbestos. "MMP9 serum levels and MMP9 polymorphisms should be further tested as a composite non-invasive diagnostic and prognostic biomarker in mesothelioma." (PMID 34572485, 2021). "Median serum MMP9 levels differed significantly before and after treatment of MM, but failed to reach significance as a standalone biomarker of treatment response in mesothelioma." (PMID 34572485, 2021). "They concluded that there is a biological role for MSLN as a factor-promoting tumor invasion and MMP-9 expression in MSLN-expressing mesothelioma tissue." (PMID 34572485, 2021). "MMP2 activity was similar in inflamed pleura and mesothelioma, but MMP9 activity was higher in inflamed pleura." (PMID 34572485, 2021). "This study investigated the influence of MMP2, MMP9, and MMP14 gene polymorphisms on time to progression and overall survival in mesothelioma patients." (PMID 29138529, 2017). "Although MMP-2, MMP-9, and MT1-MMP have been implicated in mesothelioma invasion, our results demonstrated that MT1-MMP-mediated MMP-2 activation is essential for collagen invasion and there is strong correlation between MMP-2 gene expression and invasive phenotype." (PMID 33028834, 2020). "Metalloproteinases are strongly implicated in most of the dysregulated processes in cancer, such as tumor growth, metastasis and angiogenesis and are highly expressed in mesothelioma, particularly MMP2 and MMP9." (PMID 36232554, 2022). "The most frequently investigated MMPs in mesothelioma are MMP2 (gelatinase A), MMP9 (gelatinase B), and MMP14." (PMID 34572485, 2021). "Keeping in mind the potential role of MMPs in mesothelioma and considering that only expression of MMP2, MMP9, and MMP14 has been studied in mesothelioma, we set out to perform a study exploring genetic variability of these genes." (PMID 29138529, 2017). "Different MMPs (MMP2, MMP9, MMP11, and MMP14) and their expression were studied in the mesothelioma tissue, but only a few have been prognostically significant." (PMID 29138529, 2017). "Mesothelioma MSTO-211H cells showed two bands, an intense band corresponding to MMP-2 and a faint band corresponding to MMP-9, which was significantly enhanced with PMA treatment." (PMID 23563849, 2013). "Mesothelioma pro-MMP2 and active MMP2 levels were significantly higher than MMP9 levels." (PMID 34572485, 2021). "The crucial involvement of MMP-2, MMP-9, and MT1-MMP in mesothelioma invasion has been investigated, but the molecular events leading to the acquisition of the invasive behavior remains unknown." (PMID 33028834, 2020).
metastatic melanoma (7 papers, 2013 to 2025). A melanoma that has spread from its primary site to another anatomic site. "It has been shown that knocking down N-cadherin expression inhibited the activities of MMP-2 and MMP-9, leading to reduced cell invasion in both primary and metastatic melanoma cell lines." (PMID 40806251, 2025). "So, we concluded that up-regulation of miR-450b and down-regulation of PAX9 and BMP4 were interconnected with the high MMP9 expression in metastatic melanoma cells." (PMID 31569419, 2019). "Matrix metalloproteinase-9 (MMP-9) expression was induced at acidic extracellular pH in mouse metastatic melanoma cells through phospholipase D-mitogen-activated protein kinase signaling." (PMID 24705103, 2013). "We also found that the circulating levels of MPO, MMP-9, GM-CSF and CXCL8/IL-8 were higher in metastatic melanoma patients than in healthy controls." (PMID 37525065, 2023). "Furthermore, serum concentrations of neutrophil-related factors (MPO, MMP-9, CXCL8/IL-8 and GM-CSF) and NET biomarkers (nucleosomes and CitH3) were higher in stage IV metastatic melanoma patients than in healthy controls." (PMID 37525065, 2023). "Moreover, ArcA significantly inhibited cell migration and invasion in metastatic melanoma cell lines, accompanied by reduced expression levels of p-GSK-3β (Ser9), MMP-9, and MMP-13, suggesting that its anti-metastatic effects may be partially mediated through GSK-3β, MMP-9, and MMP-13." (PMID 39948552, 2025).
Moyamoya disease (7 papers, 2021 to 2024). Moyamoya disease (MMD) is a rare intracranial arteriopathy involving progressive stenosis of the cerebral vasculature located at the base of the brain causing transient ischemic attacks or strokes. "Plasma and serum MMP-9 levels are elevated in Moyamoya disease, and MMP-9 regulates angiogenic and angiogenic processes by targeting collagen IV and other extracellular matrices, leading to pathological angiogenesis in Moyamoya disease." (PMID 38326520, 2024). "The main findings of this study are as follows: (a) DSG2 level decreased in patients with Moyamoya disease, (b) DSG2 affects PI3K signaling in vascular endothelial cells, and (c) MMP-9 is involved in DSG2-mediated vascular changes in Moyamoya disease." (PMID 38326520, 2024). "Taken together, these results suggest that DSG2 affects PI3K signaling in vascular endothelial cells, and MMP-9 is involved in DSG2-mediated vascular changes in Moyamoya disease." (PMID 38326520, 2024). "Our results indicate that DSG2 affects PI3K signaling in vascular endothelial cells, and MMP-9 is involved in DSG2-mediated vascular changes in Moyamoya disease." (PMID 38326520, 2024). "The complex of NGAL/MMP-9 was also evaluated in the urine and CSF of pediatric patients with moyamoya disease." (PMID 37445650, 2023). "Of the 19 moyamoya disease patients with MMP-9 measurements in CSF, levels in all patients ranged from 2.9 to 27.0 ng/mL." (PMID 33868159, 2021). "Median levels of urinary MMPs and VEGF were significantly higher among moyamoya disease patients (all P < 0.001, except MMP-9, P = 0.005, Mann–Whitney U-tests)." (PMID 33868159, 2021). "Multiple stepwise logistic regression confirmed that, controlling for age and gender, MMP-9 was independently predictive of moyamoya disease (P = 0.003)." (PMID 33868159, 2021). "A significantly higher percentage of moyamoya disease patients (17 of 32 = 53%) were positive for MMP-9 compared to controls (1/14 = 7%) (P = 0.003)." (PMID 33868159, 2021). "In addition, we concluded that DSG2 is protective for vascular endothelial cells via PI3K signaling, and MMP-9 is involved in DSG2-mediated vascular changes in Moyamoya disease." (PMID 38326520, 2024). "The study of Sesen provided the hypothesis that the NGAL/MMP-9 complex may be useful as a predictor of the presence of moyamoya disease and may enable the monitoring of the process of treatment." (PMID 37445650, 2023). "utilized enzyme-linked immunosorbent assay to demonstrate that upregulated matrix metalloproteinase-9 (MMP-9) expression may contribute to the development of pathologic angiogenesis and/or destabilization of vascular structure, thereby potentially leading to bleeding in moyamoya disease." (PMID 38467737, 2024). "Similarly, whereas only 2 of 14 controls were positive for MMP-9/NGAL, all 20 of the moyamoya disease patients tested were positive (P < 0.001)." (PMID 33868159, 2021).
muscular dystrophy (7 papers, 2014 to 2023). Muscular dystrophy (MD) refers to a group of more than 30 genetic diseases characterized by progressive weakness and degeneration of the skeletal muscles that control movement. "TIMP1/2, natural inhibitors of matrix metalloproteinases (MMPs), are good candidates because upregulation of MMP9 is reported to promote fibrosis in muscular dystrophy." (PMID 34627382, 2021). "Although MMP9 probably plays a differential role during the progression of muscle degeneration, its primary effect in muscular dystrophy appears to be the promotion of inflammation, tissue remodeling, and reactive myofibrosis." (PMID 32916630, 2020). "This confirms MMP9 as a good biomarker candidate for secondary changes in muscular dystrophy due to sterile inflammation and fibrotic changes." (PMID 32916630, 2020). "Under pathological conditions, such as cancer and muscular dystrophies, DG may be the target of metalloproteinases MMP-2 and MMP-9, contributing to disease progression." (PMID 29447293, 2018). "Furthermore, inhibition of MMP-9 suppressed the gene expression of MMP-3 and MMP-12 in the heart of mdx mice which is further suggestive of a cooperative interaction between various MMPs in the settings of muscular dystrophy." (PMID 25364719, 2014). "Although the mechanisms leading to the increased levels of MMP-9 remain unknown, proinflammatory cytokines whose abundance is increased in mdx mice, appear to be some of the potential stimuli for up-regulation in MMP-9 levels in skeletal and cardiac muscle in muscular dystrophy." (PMID 25364719, 2014).
neuropathic pain (7 papers, 2012 to 2024). Chronic pain caused by damage to nerve fibers. "While a pathophysiological role of MMP-2 and MMP-9 has been demonstrated in neuropathic pain, the relevance of these metalloproteinases in chronic inflammatory pain is still elusive." (PMID 22353423, 2012). "MMP-9 induces early-phase neuropathic pain by activating interleukin (IL)-1β and microglia in the early phase, while MMP-2 is implicated in the development of late-phase neuropathic pain." (PMID 39654618, 2024). "Therefore, PC may inhibit MMP-9/2 not only directly on protein activity but also at transcriptional level, both of which are beneficial to the treatment of neuropathic pain." (PMID 29929563, 2018). "Of the 47 investigated proteins, 21 (cathepsin S, CCL2, CCL4, CCL16, CFIII, CXCL5, cystatin B, E-Selectin, Fas/TNFRSF6, follistatin, GDF-15, GH, ICAM1, IL8, KLK5, MMP2, MMP9, P-Selectin, sortilin, TIMP4 and VEGF) were detectable by multiplex SP-PLA in ≥ 95% of the neuropathic pain patient samples." (PMID 26914813, 2016). "Previous studies have shown that MMP-9 and MMP-2 have been considered key molecules for the onset and maintenance of neuropathic pain inhibition of astrocytes activation and could effectively attenuate neuropathic pain." (PMID 28859670, 2017).
non-alcoholic steatohepatitis (7 papers, 2014 to 2025). "Particularly in patients with non-alcoholic steatohepatitis, serum matrix metalloproteinase-9 (MMP-9) levels were significantly higher than those in the control group (12.6 ± 6.5 vs. 8.1 ± 3.5 μg/L, p < 0.01)." (PMID 40786638, 2025). "The level of MMP-9 in patients with nonalcoholic steatohepatitis (NASH) is significantly higher than that in patients with hepatitis C, and the enzyme is mainly localized in neutrophils in the liver tissues of patients with NASH." (PMID 37090698, 2023). "In NAFLD and nonalcoholic steatohepatitis, MMP-9 and -10 were found at significantly higher levels than in chronic viral hepatitis B and C." (PMID 34065048, 2021). "Similarly, MMP-9 has been found to be significantly elevated during hepatic fibrogenesis in patients with non-alcoholic steatohepatitis (NASH) and chronic hepatitis B." (PMID 35625637, 2022). "This suggests a direct effect of the core protein on the regulation of MMP-9 protein synthesis and could explain the elevated levels of hepatic MMP-9 in biopsies from patients with HCV not observed in patients with nonalcoholic steatohepatitis." (PMID 34065048, 2021).
peripheral arterial disease (7 papers, 2011 to 2023). A disorder of the arteries supplying the upper and lower extremity and the visceral organs. "Systemic concentrations of MMP-2 and MMP-9 were also increased in peripheral arterial disease and HTN, which are present in a significant proportion of patients with T2D." (PMID 34069322, 2021). "Increased circulating levels of MMP9, however, have been reported in patients with ACSs and peripheral arterial disease." (PMID 31935243, 2020). "Plasma levels and zymographic activities of MMP-2 and MMP-9 are increased in T2D patients with peripheral arterial disease in comparison with healthy control subjects, and MMP-9 may be a useful marker for development of macrovascular complications in T2D." (PMID 32403389, 2020). "MMP2 and MMP9 concentrations and activities (zymography) were measured in the serum of T2D patients with or without peripheral artery disease (PAD)." (PMID 37445827, 2023).
pterygium (7 papers, 2020 to 2025). A wedge-shaped fibrovascular lesion arising from the bulbar conjunctiva and extending to the cornea. "As such, MMP-2 and MMP-9 are tightly linked to the progression of pterygium in ocular diseases." (PMID 40565017, 2025). "The upregulation of this gene was followed by that of genes involved in the extracellular matrix structure, COL10A1, and remodeling, MMP9, reflecting intensive fibrosis, the main pathological finding of pterygium." (PMID 40243577, 2025). "By contrast, increased levels of MMP-2 and MMP-9 are observed in fibroblasts from pathologically advanced stages of pterygium." (PMID 40565017, 2025). "During pterygium progression, fibroblasts localized to the lesion show significantly upregulated MMP-9 expression." (PMID 40565017, 2025). "In fact, MMP-2 is specifically overexpressed in the epithelium and MMP-9 is abundant in pterygium vascular endothelium and inflammatory cells." (PMID 38611627, 2024). "Previous study also shows that IL-1β promotes the matrix metallopeptidase-9 (MMP-9) production and migration of pterygium fibroblasts." (PMID 36768371, 2023). "Additionally, the co-expression of MMP-2 and MMP-9 is markedly enhanced in pterygium fibroblasts compared to normal fibroblasts." (PMID 40565017, 2025). "In this study, multiple types of MMPs (MMP2, MMP3, MMP8, MMP9, MMP11, MMP16, and MMP28) were highly expressed in pterygium." (PMID 33790949, 2021). "Expressions of MMP-2 and MMP-9 are absent in early-stage pterygium and in cultured fibroblasts." (PMID 40565017, 2025).